RRM1 (ribonucleotide reductase catalytic subunit M1)
Diseases named in the same sentence as RRM1 in open-access papers (continued):
Sharing a sentence is not in itself a finding about the gene and the disease.
tumor (107 papers, 2007 to 2026). "Our analysis of tumor mutational spectra revealed two different signatures, one closely resembling a signature from a human cancer with a mutation at the same residue in RRM1 (Y285C)." (PMID 39360631, 2024). "RRM1 gene mutation leads to unrestricted proliferation of the tumor cells, accelerates angiogenesis, and promotes metastasis." (PMID 36973651, 2023). "It was found that the presence of TUBB3 and RRM1 deletion in tumor biopsy material is associated with more effective treatment." (PMID 35204496, 2022). "Gross examination of both 273 and H1048 + siRRM1 tumors revealed a dramatic loss of SCLC pathology, whereas the RRM1 expression was confirmed in the formed tumor." (PMID 34188151, 2021). "TMB‐H was associated with RRM1 negativity in 1 of 40 tumor types and hence the combination of immunotherapy and gemcitabine is likely to be of benefit in this tumor types." (PMID 31479512, 2020). "TMB‐H was associated with RRM1 positivity in 8 of 40 tumor types and hence the combination of immunotherapy and gemcitabine is unlikely to be of benefit in these tumor types." (PMID 31479512, 2020). "The association between RRM1 expression and prognosis in the present study was consistent with previous studies investigating other tumours treated with gemcitabine." (PMID 31340801, 2019). "In several studies, RRM1 levels were found to be inversely correlated with tumor response to gemcitabine treatment, and increased RRM1 expression was associated with gemcitabine resistance in various cell lines." (PMID 26001082, 2015). "In terms of the tumor susceptibility to chemotherapy, the response rate in the low-RRM1-expression group was significantly greater than in the high-expression group (52.9% versus 5.9%, χ2 test, P = 0.007)." (PMID 24591771, 2014). "The observed variability in chemosensitivity seems to partly depend on the proportion of malignant cells in the samples and RRM1 levels but other factors associated with individual tumor heterogeneity are probably also important." (PMID 25253633, 2014). "A study demonstrated that low expression levels of RRM1 were a favorable indicator for tumor response to gemcitabine, whereas high levels were associated with drug resistance." (PMID 24649266, 2013). "RRM1 expression was also significantly associated with number of lymph nodes involved, tumor size, Ki67 expression, histological subtype and histological grade." (PMID 23922955, 2013). "Meanwhile, RRM1 expression was significantly associated with lymph node involvement, tumor size, Ki67 expression, histological subtype and histological grade in the GC tissue samples (p<0.05)." (PMID 23922955, 2013). "Meanwhile, RRM1 was associated with the number of lymph nodes involved, tumor size, Ki67 expression, histological subtype and histological grade in the ZJU set (p<0.05 for each)." (PMID 23922955, 2013). "The overexpression of RRM1 mRNA in tumor tissues is reported to be associated with gemcitabine resistance." (PMID 20226083, 2010). "RRM1 expression level is associated with gemcitabine resistance in tumor cells." (PMID 24591771, 2014). "Preclinical research has indicated that increased tumor expression of RRM1 is the major determinant of resistance to gemcitabine, and two cell line studies have demonstrated an association between gemcitabine resistance and gene amplification of RRM1." (PMID 24215511, 2013). "However, several studies have also shown that a highly expressed RRM1 might be associated with a better outcome for some cancer patients, suggestive of a suppressor role of tumor initiation, invasion and metastasis." (PMID 31637211, 2019). "This evidence suggests a RRM1-mediated reduction on tumour fibrosis, particularly decreasing collagen density, and liver metastatic foci in BBIT20-treated PDAC." (PMID 40275348, 2025).
tumor (continued). "Clinical studies have reported that patients exhibiting low RRM1 expression in tumor tissues experience improved survival and better therapeutic outcomes when treated with gemcitabine and platinum-based therapies." (PMID 39935429, 2025). "Targeting RRM1 in combination with dacarbazine significantly inhibited tumor growth in nude mouse xenograft models." (PMID 40204724, 2025). "We initially determined that DSB induces the expression of RRM1, and knockdown of RRM1 upregulated DNA damage response, further triggering significant growth inhibition following IR in tumor cells." (PMID 39695160, 2024). "The high recurrence of genes like C1QBP and RPS3A in Luminal A, USP31 and RRM1 in Luminal B, and PSMD8 and YME1L1 in Basal subtypes highlights the subtype-specific regulatory networks that underlie tumor progression." (PMID 39596229, 2024). "Heterozygous Rrm1+/Y285A mice exhibited distinct alterations in dNTP pools across various organs, shorter lifespans and earlier tumor onset compared with wild-type controls." (PMID 39360631, 2024). "Given that HR deficiency and PARP inhibitors exert a synergistic lethal effect on tumor cells, we sought to assess the response of RRM1 knockdown cells to PARPi." (PMID 39695160, 2024). "For instance, studies have shown that knocking down RRM1 leads to the upregulation of DNA damage response genes, resulting in the inhibition of tumor cell growth." (PMID 39695160, 2024). "RRM1 is expressed in almost all tumor cells, but its expression levels and functions are differently affected by tissue origin and cell location." (PMID 38274374, 2024). "Knocking down RRM1 increases DNA damage in tumor cells, while upregulating the expression of DNA damage-responsive genes and prolonging the DNA damage repair process, indicating RRM1’s involvement in DNA damage repair." (PMID 39695160, 2024). "The results showed that the levels of AGTRAP, DIVERSIN, NEDD8c and RRM1 were significantly higher in the tumour tissues compared to the healthy brain parenchyma." (PMID 38672281, 2024). "AGTRAP, DIVERSIN, cytoplasmic NEDD8 (NEDD8c) and RRM1 were significantly overexpressed in tumour tissues compared to the healthy brain, while the opposite was observed for ALKBH3." (PMID 38672281, 2024). "RRM1 is often considered as a tumor suppressor gene inhibiting tumor cell proliferation, metastasis, and invasion, and is used as the main target of antitumor drugs." (PMID 38274374, 2024). "We discovered a novel function of RRM1 in DNA damage repair, wherein it regulates HR and promotes tumor cell survival by modulating the transcription of RAD51AP1." (PMID 39695160, 2024). "It detects the mutation of tumor driver genes EGFR and KRAS and the expression of drug resistance proteins ERCC1 and RRM1, respectively." (PMID 37854320, 2023). "The expression of RRM1 T52A showed slight effects on tumor growth, which is consistent with the observations that the T52A mutation had limited effects on RNR activity in the absence of AMPK activation." (PMID 37737247, 2023). "High expression of RRM1 and RRM2 was notably associated with high tumor grade, high stage, short overall survival, and disease-specific survival." (PMID 36713030, 2023). "As a key enzyme catalyzing the transformation of ribonucleotide diphosphates to deoxyribonucleoside diphosphates, RRM1 is involved in cell migration, tumor and metastasis development, and DNA synthesis." (PMID 35915092, 2022).
tumor (continued). "We selected BIU-87 cells to evaluate the effect of down regulating TOP2A and KK47 cells to evaluate the effect of up regulating RRM1 to estimate the correlation between the expression of these two genes and tumour sensitivity to pirarubicin and gemcitabine." (PMID 35711974, 2022). "It is believed that targeting RRM1 can disrupt the antioxidant resistance system of tumor cells to mediate the onset of ferroptosis and thus radiosensitize tumor cells." (PMID 36589232, 2022). "Recently, the expression of genes such as TYMS, RRM1, TUBβ3, and EGFR was found to be associated with tumor histological type (at p < 0.05) and progression-free survival rates." (PMID 36294786, 2022). "Among the 40 patients treated with gemcitabine, the recurrence rate of tumours with RRM1 overexpression was 66.7%, whereas the recurrence rate of tumours with low RRM1 expression was 27.3% (p ≤ 0.05)." (PMID 35711974, 2022). "Forty patients underwent intravesical chemotherapy with gemcitabine; of these patients, 18 had tumours that positively expressed RRM1, and 22 had tumours that negatively expressed RRM1." (PMID 35711974, 2022). "We also investigated the functions of RRM1 or RRM2 in vivo and found that tumor growth was inhibited following knockdown of RRM1 and RRM2, compared with the control group." (PMID 35546402, 2022). "RRM1 expression increases as tumor cells acquire resistance against chemotherapeutic agents including gemcitabine." (PMID 34111175, 2021). "A human tumor xenograft model was prepared by implanting RRM1 highly expressed tumors, derived from RT112 cells, in nude mice." (PMID 33921102, 2021). "Infection with Ad-shRRM1 effectively downregulated RRM1 expression, significantly inhibiting cell growth in both RRM1 highly expressed tumor cells." (PMID 33921102, 2021). "In line with this, gemcitabine-treated tumours from KPC mice expressed high levels of RRM1 and reduced levels were observed in KPCG mice upon treatment with CBD." (PMID 34259916, 2021). "In vivo, Ad-shRRM1 treatment had pronounced antitumor effects against RRM1 highly expressed tumor xenografts (p < 0.05)." (PMID 33921102, 2021). "There were 81 tumour samples successfully processed for RRM1 analysis, and 21.0% (17/81) of the patient demonstrated high RRM1 expression." (PMID 31340801, 2019). "Our data showed that high RRM1 expression was observed in less than 30% of tumours and was an unfavourable prognostic factor for PFS." (PMID 31340801, 2019). "The most common tumor molecular profile was low RRM1 and ERCC1 (44.4%), and these patients were treated with a doublet of gemcitabine and oxaliplatin." (PMID 31065624, 2019). "While RRM2 overexpression is tumorigenic, leading to lung neoplasms in vivo, RRM1 reduces tumor formation, migration, and metastasis [reviewed in Ref." (PMID 29720963, 2018). "It has also been shown that BMI1 regulates intra-tumor RRM1 levels, which are predictive of gemcitabine therapeutic efficacy." (PMID 28445986, 2017). "The expression of RRM1 is increased in some tumor types and seems to correlate with cell proliferation." (PMID 28878380, 2017). "RRM1 is involved in carcinogenesis, tumor progression, and induces metastasis suppression though PTEN-regulated pathways." (PMID 29158875, 2017). "Patients with low tumor RRM1 expression assessed using either qRT‐PCR or IHC survived 3.94 months longer (95% CI, 2.15–5.73; P = 0.001) than those patients with high RRM1 expression." (PMID 27335251, 2016). "This is consistent with the results from early stage NSCLC studies, and this implication is supported by the role of RRM1 as a tumor suppressor." (PMID 26658059, 2015). "Data from numerous clinical studies showed that RRM1/2 expression in tumor cells is inversely correlated to the sensitivity of the tumor cells to gemcitabine therapy." (PMID 26658059, 2015).
tumor (continued). "The results indicated that RRM1 expression levels between peripheral blood and tumor tissue were linearly correlated (R2 = 0.045, P = 0.048) and similar linear correlations were observed for BRCA1 expression (R2 = 0.021, P < 0.001)." (PMID 24591771, 2014). "These two preparations contained similar amounts of tumor cells, had similar reactivity to RRM1 and ERCC1, and similar resistance to the tested drugs." (PMID 25253633, 2014). "Preclinical studies have shown that patients with low tumor tissue RRM1 expression had greater median length of disease progression and median survival time than did patients with high tumor tissue RRM1 expression." (PMID 24591771, 2014). "RRM1 depletes difluorideosycytidine 5-diphosphate and promotes DNA synthesis, thereby enabling tumor survival." (PMID 24647522, 2014). "Our study also confirmed previously suggested evidence of the relationship between tumor tissue RRM1 expression levels and gemcitabine and carboplatin combination chemotherapy prognosis, which can be demonstrated through peripheral blood RRM1 levels." (PMID 24591771, 2014). "The linear correlations of the relative expression of mRNA were observed between peripheral blood and tumor tissue expression levels for RRM1 and BRCA1." (PMID 24591771, 2014). "Linear correlations were observed between peripheral blood and tumor tissue expression levels for RRM1 (R2 = 0.045, P = 0.048) and BRCA1 (R2 = 0.021, P = 0.001)." (PMID 24591771, 2014). "Nonetheless, in these two trials, the number of considered genes was limited to ERCC1 or both ERCC1 and RRM1 that seem unlikely representing an extensive view of the biological tumor heterogeneous behavior." (PMID 25674536, 2014). "Here, the TNM stage was considered to be the output (stage III&IV vs. stage I&II), and the odds ratio (OR) for RRM1 (RRM1-high vs. RRM1-low) was adjusted for co-factors, including age, sex, tumor location and histological grade." (PMID 23922955, 2013). "Based on the importance of the biomarkers involved in gemcitabine metabolism, we assessed the expressions of three key molecules (hENT1, dCK, and RRM1) in tumor samples from 28 patients with advanced BTC who received first-line gemcitabine monotherapy." (PMID 23710668, 2013). "The primary objective was to assess the objective response rate (ORR), while EGFR and KRAS mutations and mRNA and protein expression levels of ERCC1 and RRM1 were analyzed in tumor tissues and blood samples." (PMID 23621919, 2013). "Increased RRM1 predicts for decreased tumor invasiveness and metastatic potential, therefore predicting for more indolent behavior, perhaps mediated through its direct correlation with phosphatase and tensin homolog (PTEN) protein expression." (PMID 26316937, 2012). "Retrospective studies of stage IV NSCLC patients treated with gemcitabine-based chemotherapy have shown that patients with low tumor RRM1 mRNA levels lived longer than patients with higher expression levels." (PMID 20226083, 2010). "Nevertheless, it is difficult to ordinarily use tumor RRM1 mRNA levels as a predicator to determine optimal chemotherapy regimens in clinical practice." (PMID 20226083, 2010). "Studies had identified that overexpression of both mice R1 and human RRM1 significantly inhibited in vivo tumor growth and decreased metastatic potential of tumor through activating PTEN pathway." (PMID 19250552, 2009). "The results of the present study are along the lines of several other reports demonstrating that tumour mRNA expression of RRM1 was correlated with clinical response to gemcitabine/cisplatin in stage IV NSCLC." (PMID 18414411, 2008). "Their results suggest that ERCC1 and RRM1 expression evaluated by real-time RT-PCR are predictors of tumor response in patients treated with the gemcitabine-platinum doublet regimen." (PMID 19578506, 2008).
tumor (continued). "A prospective, phase II clinical trial that used tumor expression of RRM1 and ERCC1 mRNA as detected by real-time quantitative polymerase chain reaction (RT-QPCR) for selection of chemotherapy in advanced NSCLC patients has been recently conducted." (PMID 19452042, 2008). "Additionally, RRM1 inhibition enhances DAC-mediated tumor suppressor gene reactivation and STING pathway activation via DNA damage-induced IFI16 sensing." (PMID 41748545, 2026). "Tokunaga, Y constructed an adenoviral vector that encoded a short hairpin siRNA targeting the RRM1 gene (Ad-shRRM1) that increased sensitivity to gemcitabine of each type of RRM1-overexpressing tumor cell NSCLC lines and human tumor xenograft model in nude mice." (PMID 40248194, 2025). "The total number of mutations in this tumor sample is only 113, which supports the notion that RRM1-Y285C mutation does not lead to a strong mutator phenotype." (PMID 39360631, 2024). "All four individual siRNAs targeting RRM1 or RRM2 caused a reduced viability in the tumor cell lines but not in the normal PO fibroblasts." (PMID 38992100, 2024). "Furthermore, upregulation of Gemcitabine transport protein (ENT1 and RRM1) on tumor cells leads to increased drug bioavailability of PDAC cells." (PMID 37156839, 2023). "For instance, RRM1 knockout could inhibit tumor growth, reduce the risk of metastasis and increase the sensitivity to chemotherapeutic drugs—indicating that RRM1 had pro-tumor functions." (PMID 35204799, 2022). "Tumour expression of TOP2A, RRM1, HER2 and ERCC1 may associated with the sensitivity of NMIBC to pirarubicin or gemcitabine treatment." (PMID 35711974, 2022). "In addition, a better response to gemcitabine was observed in the tumours with a low expression of both RRM1 and ERCC1." (PMID 35711974, 2022). "Gemcitabine was effective in tumours with low RRM1 expression." (PMID 35711974, 2022). "The low expression of RRM1 may limit the function of DNA repair, which reduces the ability of tumour cells to be more sensitive to chemotherapeutic drugs." (PMID 35711974, 2022). "Similarly, RRM1 knockout in H1048 cells decreased the rate of tumor formation in nude mice compared with cells expressing the siCont control." (PMID 34188151, 2021). "Interestingly, ribonucleotide reductase large subunit 1(RRM1) and cytochrome p450 2W1 (CYP2W1) expression levels has been associated with response to mitotane therapy and prolonged tumor-free survival." (PMID 33591997, 2021). "Because the loss of RRM1 expression in vitro inhibited SCLC cell growth, we investigated the role of RRM1 in tumor growth in vivo using an immunodeficient nude (nu/nu) murine xenograft model subcutaneously transplanted with human SCLC cells with in vivo siRNA delivery." (PMID 34188151, 2021). "For RRM1, the Fisher's exact test was significant in 9 of 40 tumor types." (PMID 31479512, 2020). "For RRM1, the Fisher's exact test was significant in 5 of 40 tumor types." (PMID 31479512, 2020). "PD‐L1 expression was associated with RRM1 positivity in 5 out of 40 tumor types; hence, gemcitabine and immunotherapy is unlikely to be of benefit." (PMID 31479512, 2020). "Moreover, decreased expression was associated with tumor size/diameter and levels of serum CEA, CA19-9, and tissue RRM1." (PMID 26472090, 2015). "Therefore, the association between ERCC1, TYMS, RRM1, TUBB3 and TOP2A expression levels with the pathogenesis and development of ESCC was investigated using a clustered analysis in terms of tumor invasion and lymphatic and distal metastasis." (PMID 24926347, 2014). "Tumor RRM1, ERCC1, and BRCA1 mRNA expression levels were analyzed by quantitative RT-PCR." (PMID 24591771, 2014). "A significant inhibition (approximately 40 %) was seen for both the sequence and combination treatments, suggesting that inhibition of RRM1 expression by LY2835219 may be sensitizing tumor cells to the activity of gemcitabine." (PMID 24919854, 2014).